C5 (complement C5)
Diseases named in the same sentence as C5 in open-access papers (continued):
Sharing a sentence is not in itself a finding about the gene and the disease.
meningococcal infection (continued). "Thus far, proximal complement inhibition with pegcetacoplan has not displayed a significant increase in meningococcal infections compared with C5 inhibitors; however, definitive conclusions are limited given the low event rate." (PMID 38812989, 2024). "Event rates for thrombosis were comparable between pegcetacoplan and previously reported rates of C5 inhibitors in patients with PNH, and no cases of meningococcal infection were reported with pegcetacoplan." (PMID 38812989, 2024).
anemia (22 papers, 2013 to 2025). A reduction in the number of red blood cells, the amount of hemoglobin, and/or the volume of packed red blood cells. "The anti-C5 MoAb eculizumab was the first drug to reduce hemolysis, improve anemia, and abate thrombotic risk in PNH patients." (PMID 36698833, 2022). "Phase II trials have shown that iptacopan eliminated intravascular hemolysis in PNH patients and reduced extravascular hemolysis in patients with persistent anemia who had been treated with C5 complement inhibitors." (PMID 40837563, 2025). "Anti-C5 therapy led to remission of anemia and thrombocytopenia in about 90% of patients, C3 normalization in 90%, and dialysis independence in 74%." (PMID 41333025, 2025). "Pegcetacoplan has shown superior efficacy over eculizumab in patients with PNH with persistent anemia despite C5 inhibition, yet human pregnancy data are limited to a single case report, which did not include pharmacokinetic analysis." (PMID 41268092, 2025). "In real-world patients receiving PEG as second-line therapy due to anemia experienced during C5 inhibition, one study revealed that 13 out of 48 patients experienced breakthrough hemolysis while receiving PEG or combination therapy with C5 inhibitors." (PMID 39584922, 2024). "Pegcetacoplan is a self-administered, twice weekly (1080 mg subcutaneous [SC]) infusion and is licensed in Europe for the treatment of adult patients with PNH whose anaemia is uncontrolled after treatment with a C5 inhibitor for ≥ 3 months." (PMID 37195551, 2023). "The AC recommended pegcetacoplan as an option for the treatment of PNH in adults who have uncontrolled anaemia despite treatment with a stable dose of a C5 inhibitor for ≥ 3 months." (PMID 37195551, 2023). "This article includes a summary of the ERG report and the AC’s final decision for the FTA of pegcetacoplan for treating paroxysmal nocturnal haemoglobinuria (PNH) in adults whose anaemia is uncontrolled after treatment with a C5 complement inhibitor." (PMID 37195551, 2023). "In March 2022, NICE recommended pegcetacoplan for the treatment of PNH in adults who have uncontrolled anaemia despite treatment with a stable dose of a C5 inhibitor for ≥ 3 months." (PMID 37195551, 2023). "Eculizumab and ravulizumab are anti-C5 monoclonal antibodies that inhibit the terminal complement system, reducing hemolysis, anaemia, occurrence of thrombosis and PNH-related mortality." (PMID 37854608, 2023). "Proximal inhibitors (C3, factor B and D inhibitors) show dramatic efficacy on extravascular hemolysis and in improving residual anemia while on anti-C5 agents." (PMID 36698833, 2022). "However, persistent anemia has become a new challenge for patients who have received C5 complement inhibitors." (PMID 40837563, 2025). "Eculizumab, the first approved C5 inhibitor, significantly reduced thrombotic risk and improved survival but did not eliminate anemia due to extravascular hemolysis." (PMID 41002734, 2025). "For example, LDH may be significantly decreased or even normalised following the initiation of a C5 inhibitor, and yet anaemia may persist secondary to EVH or residual IVH." (PMID 39201278, 2024). "C5 inhibitors, the current gold standard of therapy, target underlying intravascular hemolysis but do not address the residual anemia brought on by insufficient management of intravascular hemolysis in some individuals." (PMID 38541105, 2024). "In patients treated with C5 inhibitors, anaemia may persist or recur as a consequence of residual IVH, or C3-mediated EVH." (PMID 39201278, 2024). "Thus, anemia and thrombophilia are usually well-controlled by C5 inhibition, but in some patients, transfusion-dependent anemia persists." (PMID 38954058, 2024). "The US Food and Drug Administration (FDA) approved pegcetacoplan in 2021 for the treatment of adults with PNH, shortly followed by the European Medicines Agency (EMA)’s approval of it in 2021 for adults with PNH who had anemia after at least 3 months of C5 inhibitor therapy." (PMID 39201383, 2024).
anemia (continued). "Expert reviews have estimated that up to one third of C5 inhibitor-treated patients will develop EVH, although surveys of patients receiving at least 3 months of C5 inhibitor therapy suggest that anaemia and fatigue persist in an even greater proportion of patients." (PMID 39201278, 2024). "However, persistent anemia remains a significant clinical challenge in a subset of patients treated with C5 inhibitors, primarily due to EVH, a phenomenon driven by C3 fragment deposition on RBCs and their subsequent removal by the mononuclear phagocyte system." (PMID 41002734, 2025). "In May 2021, the company (Apellis Pharmaceuticals/Sobi) provided a submission to NICE describing the use of pegcetacoplan (within the context of its licensed indication) in patients with PNH who had uncontrolled anaemia after treatment with a C5 inhibitor for a period of ≥ 3 months." (PMID 37195551, 2023). "Our results indicated that LBZT exerts therapeutic effects against anemia by regulating the expression of complement C1QA, C1QC, C5, C8A and C8B and the subsequent complement and coagulation cascades." (PMID 39021933, 2024). "Factor B inhibitor iptacopan, and factor D inhibitor danicopan have been shown to improve anemia and reduce hemolysis and transfusion needs in PNH patients who are suboptimal responders to anti-C5 in early phase trials." (PMID 36698833, 2022). "In the last decade, ECU, a monoclonal antibody against C5 complement fraction, has revolutionized PNH natural history, reducing the incidence of anemia, transfusion dependency, and thrombosis, and thus increasing patients’ quality of life." (PMID 33804461, 2021). "Additionally, approximately 50% of patients treated with C5 inhibitors develop EVH, attributed to C3d deposition on RBCs, leading to persistent anemia and transfusion dependency." (PMID 41002734, 2025). "Over 50% of anti-C5 treated patients might have C3d deposition on their red cell shown by direct antiglobulin (DAT) testing and 10%–30% will continue to experience anemia and require transfusions mainly because of extravascular hemolysis (EVH)." (PMID 39734592, 2024). "Previous treatments for PNH include C5 inhibitor therapies such as eculizumab and ravulizumab; however, C5 inhibitors do not address extravascular hemolysis, resulting in persistent anemia in certain individuals." (PMID 39584922, 2024). "In these patients, anaemia is not due to uncontrolled complement activity and is unlikely to respond to higher doses of C5 or C3 inhibitors." (PMID 37195551, 2023). "In conclusion, the PADDOCK and PALOMINO trials demonstrate that daily subcutaneous pegcetacoplan injection is an effective treatment for PNH-related anemia in patients not previously treated with C5 inhibitor therapy." (PMID 35869170, 2022).
Arthritis (21 papers, 2010 to 2026). Inflammation of a joint. "Blocking C5 activation using anti-C5 monoclonal antibodies prevented arthritis onset in susceptible mice and also improved the ongoing clinical symptoms." (PMID 40592462, 2025). "Specifically, mice with targeted or naturally occurring mutations in the genes encoding factor B (of the alternative pathway), C3, C5, the C5a receptor (C5aR), and FcRγ were protected from developing serum-transferred arthritis." (PMID 23237573, 2012). "Moreover, FCGR2B deficiency counteracts Hc encoding complement C5 action to accelerate the rapid progression of arthritis." (PMID 39734218, 2024). "Studies using C3−/− and C5−/− mice models have demonstrated that C3-independent C5 activation occurs in some diseases like acute lung injury, LPS-induced fetal loss, and autoantibody-meditated arthritis." (PMID 35087765, 2021). "However, in those diseases mediated by thrombin that have a C3-independent C5 activation, such as acute lung injury, LPS-induced fetal loss, and autoantibody-meditated arthritis, C3−/− mice still had the same disease susceptibility as wild-type mice." (PMID 35087765, 2021). "Evidence from experimental models also implicates complement in RA; anti-C5 Ab ameliorated disease in mouse collagen-induced arthritis in mice-ameliorated disease, and C5-deficient mice were refractory to collagen-induced arthritis." (PMID 25725109, 2015). "This was further confirmed by blockade of C5 with anti-C5 mAb, which both prevented disease by treatment prior to onset and reversed ongoing disease when injected several days after arthritis onset." (PMID 27313578, 2016). "Here, we investigated a possible contribution of C3-independent mechanisms of C5 activation in a mouse model of autoantibody-mediated arthritis." (PMID 23237573, 2012). "Here we studied the interplay of C3, C5, and activating FcγRs in a model of spontaneous autoantibody-driven arthritis." (PMID 23237573, 2012). "The different in vivo models of RA have concordantly shown that mice deficient in complement components and related proteins (C3, factor B, C5 C5aR, and MASP1/3) are protected against the development of arthritis, with a greater protective effect for C5 than C3." (PMID 35242041, 2022). "Our group and collaborators demonstrated the successful delivery of IL-4 in vivo using a synovium targeting peptide in the xenograft SCID mouse model, and the selective accumulation of an anti-C5 antibody fused to the same synovium targeting peptide in affected joints of rodent models of arthritis." (PMID 33679801, 2021). "Moreover, complement modulation by using C3aR and C5aR antagonists and an anti-C5 blocking antibody was found to be effective in animal studies by ameliorating arthritis or even preventing the disease." (PMID 31214191, 2019). "Similarly, a fusion protein containing synovial-homing peptide and anti-C5 neutralizing antibody, which specifically targeted inflamed joints attenuated antibody initiated arthritis." (PMID 29495570, 2018). "So which component of the complement system C3 or C5 is important for the development of arthritis?" (PMID 29892280, 2018). "However, studies done with anti-C5 antibodies (Eculizumab) in arthritis gave mixed results and were published only as web release." (PMID 20975959, 2010). "In addition, treating K/BxN mice with anti-C5 monoclonal antibody reduced their arthritis severity." (PMID 23237573, 2012). "The development of arthritis in K/BxN serum-transferred mice, a model in which autoantibodies against glucose-6-phosphate isomerase play an important role, is suppressed by the deficiency of factor B, C3, C5 or C5a, but not by C1q or MBP-A, suggesting the involvement of the AP in the pathogenesis." (PMID 26404464, 2015). "Mice lacking C5 or treated with GalNAc-C5-siRNA or anti-C5 inhibitory antibody do not develop arthritis despite the presence of MASP-1 and MASP-2." (PMID 32153567, 2020).
Arthritis (continued). "While complement C5 protein is critical for development of arthritis, but not endocarditis, occurrence of endocarditis, but not arthritis, requires the participation of FcRγ." (PMID 32266270, 2020). "C5 activation, and specifically MAC formation, was demonstrated to be crucial to the development of arthritis in three mouse models of the disease, and expression of inflammatory and degradative molecules was lower in chondrocytes from destabilized joints from C5-deficient mice." (PMID 23166676, 2012). "The key finding of this study is that autoantibody-mediated arthritis in K/BxN mice can occur via a C5 activation pathway that requires neither C3 nor activating FcγRs, the two main effector mechanisms of IgG molecules." (PMID 23237573, 2012). "In K/BxN mice, C5-dependent autoantibody-driven arthritis can occur in the genetic absence of both complement C3 and activating FcγRs." (PMID 23237573, 2012). "Neutralizing antibodies induced upon immunization were specific to C5a and they did not alter C5/C5b activity significantly but led to attenuation of arthritis in various mouse models." (PMID 20975959, 2010). "Interestingly, while the arthritic phenotype of K/BxN mice is dependent on complement C5, such a pathway was not required for the development of endocarditis, which relied on FcγR, the absence of which had little impact on arthritis severity." (PMID 34526398, 2021). "Here, we could demonstrate the feasibility of generating anti-C5a antibodies by the host after immunization with C5a fusion protein that did not compromise C5/C5b activity significantly but led to attenuation of arthritis in various mouse models." (PMID 20975959, 2010).
myasthenia gravis (21 papers, 2017 to 2026). Myasthenia gravis (MG) is a rare, clinically heterogeneous, autoimmune disorder of the neuromuscular junction characterized by fatigable weakness of voluntary muscles. "Currently, complement-targeting effective therapies are available for myasthenia gravis, albeit with some limitations, including the possibility of individual resistance due to C5 mutations." (PMID 40422242, 2025). "This has led to the development of the first C5 inhibitors approved for myasthenia gravis with AchR antibodies: eculizumab, ravulizumab, and zilucoplan." (PMID 40422242, 2025). "Other C5 inhibitors with different chemical structures are currently being studied for the management of myasthenia gravis." (PMID 40422242, 2025). "For example, ecuzumab, a monoclonal antibody that inhibits the activation of terminal complement by binding to C5, has been approved for the treatment of Myasthenia gravis (MG) and multifocal motor nerve neuropathy (MMN)." (PMID 37958975, 2023). "Myasthenic crisis is a life-threatening exacerbation of myasthenia gravis leading to respiratory failure, while zilucoplan is a C5 complement inhibitor that prevents complement-mediated destruction of the neuromuscular junction, thereby helping to restore muscle function and respiration." (PMID 40190980, 2025). "The downregulation of SELL and the upregulation of C5 and HLA-A may indicate a good prognosis of postoperative myasthenia gravis." (PMID 40599774, 2025). "To date, agents targeting C5 provide the most successful therapeutic strategy, with complement treatment in myasthenia gravis (MG) and neuromyelitis optica spectrum disorders (NMOSD) being the most developed." (PMID 35204837, 2022). "Furthermore, studies showed that C5 antibodies are a promising new treatment option for patients with other neurological diseases, such as pneumococcal meningitis, neuromyelitis optica, and myasthenia gravis." (PMID 31811640, 2020). "Through screening, three proteins were found to be possibly related to the prognosis of myasthenia gravis after thymoma surgery: SELL (downregulated) and C5 and HLA-A (upregulated)." (PMID 40599774, 2025). "The anti-C5 antibody eculizumab was the first complement-specific therapeutic; while initially approved for the treatment of PNH, its indications meanwhile include aHUS, myasthenia gravis and neuromyelitis optica-related disorders." (PMID 37771595, 2023).
thrombotic microangiopathy (19 papers, 2013 to 2026). The syndromes of microangiopathic hemolytic anemia, thrombocytopenia, and variable signs of organ impairment, due to platelet aggregation in the microcirculation. "Eculizumab, a C5-blocking monoclonal antibody, is remarkably effective in the treatment of different forms of thrombotic microangiopathy by controlling complement system hyperactivation." (PMID 39318635, 2024). "The data also highlighted the role of C5 activation in the formation of thrombotic microangiopathy (TMA) in the kidney and provided a model system that allows analysis of aspects of C3G and aHUS, a phenotype that can be seen in the clinic." (PMID 36203396, 2023). "The 311 phase 3 trial (NCT02949128) showed that ravulizumab, a long-acting C5 inhibitor obtained through selective modifications to eculizumab, is efficacious in inhibiting complement-mediated thrombotic microangiopathy (TMA) in patients with aHUS." (PMID 33407224, 2021). "Atypical haemolytic uraemic syndrome (aHUS) is a form of thrombotic microangiopathy precipitated by unopposed complement activation, the treatment of which has been revolutionised by the availability of the monoclonal anti-complement (C5) antibody, eculizumab." (PMID 31687234, 2019). "This child simultaneously developed severe thrombotic microangiopathy and died of multiorgan failure at 6 months post-HSCT, despite treatment with monoclonal anti-C5 antibody (eculizumab)." (PMID 38255745, 2024). "Therapeutic blockade or genetic deletion of C5, a protein downstream of C3 in the complement cascade, protected homozygous C3KI mice from thrombotic microangiopathy and aHUS." (PMID 30714990, 2019). "In addition, eculizumab, an anti-C5 monoclonal antibody, could be effective in controlling TMA, but it remains unclear whether this monoclonal antibody would also be effective in drug-induced thrombotic microangiopathy (DITMA) until now." (PMID 38965631, 2024).
neuromyelitis optica spectrum disorder (17 papers, 2020 to 2025). "Eculizumab, a monoclonal antibody against complement C5, has been approved to prevent neuromyelitis optica spectrum disorder (NMOSD) relapse." (PMID 39534550, 2024). "Eculizumab, a C5 inhibitor is largely used in ab-mediated disease like severe resistant lupus nephritis or neuromyelitis optica and has already successfully treated patients, At the time of writing this review, one molecule has been tested in IMNM: zilucoplan." (PMID 38390873, 2024). "Eculizumab, a humanized monoclonal antibody targeting the C5 complement protein, has been approved for the treatment of neuromyelitis optica spectrum disorders (NMOSD) in adult patients who are anti-aquaporin-4 (AQP4) antibody positive (Ab+)." (PMID 38318238, 2023). "Eculizumab is an anti-C5 monoclonal antibody considered as a treatment option for neuromyelitis optica, preventing the aquaporin-4 mediated complement-induced damage." (PMID 35976311, 2022). "In a number of complement-driven inflammatory diseases, such as aHUS, PNH, and neuromyelitis optica, 2 antibody-based C5 inhibitors targeting the same epitope on C5_MG7 currently represent the only approved treatments." (PMID 31871188, 2020). "Several inhibitors targeting C1, C3, C5, and C5a have undergone development and received approval for clinical applications, although only anti-C5 therapies have received approval for CNS indications (generalized myasthenia gravis and neuromyelitis optica spectrum disorder)." (PMID 41261092, 2025).